IL6 (interleukin 6)
Diseases named in the same sentence as IL6 in open-access papers (continued):
Sharing a sentence is not in itself a finding about the gene and the disease.
depression (continued). "Cldn5 knockdown in the nucleus accumbens did not induce anxiety- and depression-like behaviors but lowered resilience to the social-stress induced depression by attenuating the paracellular barrier against blood-circulating interleukin-6 (21 kDa)." (PMID 36978081, 2023). "Third, we determined that the concentrations of IL-1β, IL-6, DIO1, and DIO3 may influence the development of depression." (PMID 37834806, 2023). "Moreover, compared with healthy controls, a higher level of IL-2, IL-6, and interferon (IFN)-γ was reported in patients with comorbid depression in COPD." (PMID 37048736, 2023). "Accordingly, depression might lead to reduced TGF-β plasma levels and, subsequently, to inflammation in CHB patients through the decreased serum levels of IL-6 and TGF-β." (PMID 38138916, 2023). "This hypothesis was supported by meta-analyses showing that cytokine concentrations, including IL6, IL1β, IL17, and TNFα, were raised in the peripheral blood of patients with depression and anxiety compared with healthy controls." (PMID 37916198, 2023). "Although not significantly altered, IL-6 levels tend to be upregulated (p = 0.0691) and IL-4 downregulated (p = 0.0746) in depression patients." (PMID 37575572, 2023). "In addition to IL-6 and glucocorticoids, the hyperglycemia seen in T2DM can also act on the brain to induce depression and obesity." (PMID 37664841, 2023). "Although classic inflammatory markers such as CRP, IL-6, and TNF-α are associated with depression and vitamin D deficiency, they do not seem to be all the mediators of this link." (PMID 37049606, 2023). "MSD has been found to activate the microglial cells and increase the expression levels of proinflammatory cytokines, including interleukin (IL)-1β, IL-6, and tumor necrosis factor-alpha (TNF-α), in the hippocampus, accompanied by depression and cognitive impairment." (PMID 37168717, 2023). "At present, the most consistent conclusion regarding the relationship between neuroinflammation and depression is that levels of proinflammatory cytokines; including TNF-α, IL-1β, and IL-6; are increased in both the plasma and central nervous system in patients suffering from MDD." (PMID 36909192, 2023). "Furthermore, we investigated the relationship between pro-inflammatory cytokines and depression by measuring the concentration of TNF-α, IL-6, and IL-1β in mice." (PMID 37173696, 2023). "For instance, TNF‐α, IL‐1β, IL‐6, and IL‐17A are elevated in coronary heart disease patients with anxiety and depression in comparison to those without these disorders." (PMID 37878890, 2023). "The current observation in our study that LAT reduces CSDS-induced increase in IL-6 and TNF-α, concomitant with the mitigation of depression-like behavior, strongly supports this hypothesis." (PMID 37400661, 2023). "IL-6 can cross the blood–brain barrier (BBB)and increase synaptic contractility by directly affecting neurons or regulating microglia and other immune cells, thereby aggravating depression." (PMID 37828513, 2023). "Regarding specific objectives, the analysis of symptoms of depression (BDI-II scale score) given the levels of CRP and IL-6 will be conducted using linear mixed models, adjusted for age, BMI, hemoglobin HbA1C, medication, physical activity, smoking and drinking habits and sex." (PMID 37016319, 2023). "A meta-analysis of cytokine alterations in the blood, based on 107 studies comprising a total of 5,166 patients with depression compared to 5,083 healthy controls, found levels of IL-3, IL-6, IL-12, IL-18 and TNF-ɑ to be higher in blood from the patients with depression." (PMID 37016363, 2023). "Spearman’s correlation analysis showed that different microbial communities (Corynebacterium, Faecalibaculum, Enterorhabdus, Desulfovibrio) correlation with differential metabolites (Cholic acid, Deoxycholic acid, etc.)and depression-related biochemical indicators (5-HT, DA, BDNF, IL-6, and TNF-α)." (PMID 37692389, 2023).
depression (continued). "Ingestion of Faecalibaculum for 14 days induced anhedonia-like and depression behaviors of ABX-treated Ephx2KO mice, accompanied by the increased expression of proinflammatory factors, such as interleukin-6 in the blood and reduction of synaptic proteins expression in the prefrontal cortex." (PMID 36937259, 2023). "Higher levels of TNF-α and IL-6 in patients with BPD and depression (P<0.05)." (PMID 36946840, 2023). "For instance, in a longitudinal study, higher levels of IL‐6 in childhood, but not CRP, were associated with increased risk of depression and psychosis in young adulthood (Khandaker, Pearson, Zammit, Lewis, & Jones, 2014)." (PMID 36597271, 2023). "Moreover, the pro-inflammatory mediators IL-6, IL-1β, and TNF-α are elevated in diabetes-induced anxiety and depression." (PMID 38105928, 2023). "Interestingly, a positive Spearman correlation was maintained at the mRNA level in PBMCs of depression patients, between CCL2, IL-6 and TNF-α." (PMID 37575572, 2023). "Higher levels of TNF-α and IL-6 in patients with BPD and current depression (P<0.05)." (PMID 36946840, 2023). "Several inflammatory markers, namely IL-1, IL-6, TNF-α, and hsCRP, have been found to be elevated in individuals with depression, and thus depression may be pathophysiologically underpinned by chronic inflammation." (PMID 37163324, 2023). "Research has also revealed a correlation between neurological state and peripheral inflammation; patients diagnosed with major depressive disorder have markedly increased peripheral blood levels of pro-inflammatory cytokines, including TNF, and interleukin-6 (IL-6)." (PMID 37274195, 2023). "Notably, ZSQGY was able to reduce the levels of IL-1β, IL-6, TNF-α, and IFN-γ, which demonstrated the anti-inflammatory effects of ZSQGY in the central nervous system in the MSG-induced depression model." (PMID 37251232, 2023). "There were also positive correlations observed between IL-6 and the mood and anxiety subscales of the CGI-S (r = 0.396, p = 0.01 and r = 0.371, p = 0.017, respectively) and the depression and anxiety subscales of the DASS-21 (r = 0.313, p = 0.047 and r = 0.389, p = 0.012, respectively)." (PMID 37107316, 2023). "Depression patients were found to have significantly higher levels of TNF-α and CCL2 in the plasma, and increased expression levels of TNF-α together with decreased IL-6, in PBMCs." (PMID 37575572, 2023). "Regarding the non-motor symptoms of PD, a previous study evaluated the non-motor symptoms using UPDRS part I and found that plasma IL-6 level was correlated with the severity of depression." (PMID 36875766, 2023). "Depression-like behavior was measured by a series of behavioral tests and neurobiochemical factors (5-HT, DA, and BDNF) and pro-inflammatory factors (IL-6 and TNF-α) were measured in brain tissues, combined with Nissl pathological analysis and determination of gut microorganisms." (PMID 37692389, 2023). "Studies have primarily assessed whether there is a relationship between the peripheral concentration of pro-inflammatory markers such as c-reactive protein (CRP), interleukin-6 (IL-6) and tumor necrosis factor-α (TNF-α) and the development of depression." (PMID 37928924, 2023). "Notably, IL-6, IL-1RA, IL-12, TNF-α, IFN-γ, IL-10, IL-1β, and IL-8/CXCL8 exhibit increased levels in both acute and chronic CHIKV cases, as well as in depression." (PMID 38088664, 2023). "Indeed, depression was recently characterized as a pro-inflammatory state in a large meta-analysis which found robust elevations of CRP, and proinflammatory cytokines IL-6, IL-3, IL-6, IL-12, IL-18, soluble IL-2 receptor, and TNF-α." (PMID 37614344, 2023). "The hypothesis being tested in this trial is that promoting adherence to the MedDiet as an adjuvant to standard treatments for MDD can reduce symptoms of depression in patients with MDD and elevated inflammation biomarkers (IL-6 and CRP)." (PMID 37016319, 2023). "IL-6 and CRP also increase in patients with anxiety and depression." (PMID 36873198, 2023).
depression (continued). "Studies have reported that IL-6, TNF-α, CRP, YKL-40, IL-17, IL-1β, CCL2, IL-2, and IL‐8 are related to worse cognitive function or cognitive deterioration, while CRP, TNF-α, sIL-2R and CCL2 reflect severe symptoms of depression and anxiety." (PMID 36739284, 2023). "IL-6, TNF-α and IFN-γ were associated with depression and suspiciousness, but not to other positive or negative symptoms, while controlling for all other symptoms in the network." (PMID 37723153, 2023). "PD patients who had a higher serum IL-6 level were more likely to experience more severe motor and non-motor symptoms, depression, and cognitive impairment." (PMID 36875766, 2023). "Reciprocally, depression might lead to reduced TGF-β plasma levels and, subsequently, induce inflammation in CHB patients through decreased serum levels of IL-6 and TGF-β." (PMID 38138916, 2023). "Pro-inflammatory cytokines such as IL-6 and TNF-α were elevated in patients with depression." (PMID 36979303, 2023). "It is not known if the improvement in depression in our study participants was mediated through a reduction in IL-6 or through other mechanisms." (PMID 37644985, 2023). "Patients with depression disorder exhibit a chronic inflammatory state which is characterized by elevated serum levels of pro-inflammatory cytokines, including TNF-α, IL-1β, IL-2, IL-6, IL-12, and decreased levels of anti-inflammatory cytokines, such as IL-10, compared to controls." (PMID 37273278, 2023). "This study aims to understand if promoting adherence to the MedDiet, as an adjuvant strategy in the treatment of MDD, is effective to decrease symptoms of depression in patients diagnosed with MDD with high levels of inflammation biomarkers, namely elevation of CRP and/or IL-6 at baseline." (PMID 37016319, 2023). "Microglia are significantly stimulated in the CNS and peripheral blood of animal models of depression such as CSDS and CUMS, and pro-inflammatory cytokines including TNF-α, IL-1 β, and IL-6 are also significantly elevated in the brain, according to a preclinical study." (PMID 35634375, 2022). ", participants with depression who were not drug-naïve showed smaller hippocampal volumes but higher IL-6 concentrations." (PMID 36261698, 2022). "Conclusion: taVNS showed effects on CRP, IL-6, and depression levels; however, it did not affect other clinical symptoms." (PMID 36295080, 2022). "In a rat model of chronic unpredictable mild stress (CUMS)-induced depression, epigallocatechin gallate (EGCG) exerted an anti-depressive effect by reducing IL-6 and nitric oxide (NO) expression levels and decreasing the mRNA expression of caspase-3 and caspase-9 in the hippocampus." (PMID 36358502, 2022). "The effect of the extract on the role of inflammatory mediators (specifically IL-2, IL-6, IL-8 and TNF-ɑ) in aggression and depression could be considered for future research." (PMID 36386158, 2022). "Considering that stress and IL-6 are closely related to the development of depressive orders, TMC3115 may be a new candidate substance for the prevention or treatment of depression in the future." (PMID 35267944, 2022). "COX-2 overexpression leads to an increase in the pro-inflammatory cytokines IL-1β, IL-6 and TNF, which increases the activity of the 5-HT transporter protein SERT, increases the affinity of the 5-HT receptor 5-HT1A, and mediates depression through an IDO mechanism that alters tryptophan metabolism." (PMID 36440427, 2022). "Cytokines IL-6 and TNF-α appeared to be good predictors for depression." (PMID 35757220, 2022). "Baicalin significantly reduced the levels of TNF-α, IL-1β, and IL-6 in depression-like hippocampal tissues by upregulating PI3K/AKT/FOXO1 pathway and inhibiting TLR4 expression and so alleviate neuroinflammation-induced depression-like behavior." (PMID 35350754, 2022).
depression (continued). "In fact, these studies saw significant correlations between depression and other inflammatory markers such as IL-6 and TNF-α, but not CRP." (PMID 35618889, 2022). "In patients with or without history of heart disease, depression is also associated with elevated cytokine levels (especially CRP, IL-1, and IL-6)." (PMID 36248418, 2022). "In addition, venlafaxine has been reported to play an anti-inflammatory role through downregulation of serum TNF-α, IL-1β, IL-6, and CRP in major depressive disorder and animal researches." (PMID 35664492, 2022). "Hypotheses such as ‘macrophage theory of depression’ and the ‘cytokine hypothesis of depression’ were proposed to describe a higher expression of IL-1, TNF‐α, IL-6, and IL-8 in patients suffering from depression." (PMID 35784295, 2022). "In the present study, the most promising biomarkers of neuroinflammation related to depression will be investigated including total CSF WCC, CSF/serum albumin ratio, CSF total protein, IgG index, CSF levels of IL-6 and IL-8, and any CNS-reactive autoantibody in CSF and/or blood." (PMID 35022028, 2022). "To investigate the differences in the expression of inflammatory factors in the serum of normal person, patients with depression, and patients with DCMI, we performed ELISA to detect the levels of NPY, T, IL-1β, IL-6, TNF-α, IL-10, and IL-4 in the peripheral blood plasma." (PMID 35432561, 2022). "Group differences regarding TNF-α but not IL-6 were observed, and partial correlation analysis indicated an association between TNF-α and clinician-rated depression scores over the complete sample when controlling for age, weight, and height." (PMID 35444568, 2022). "Depression leads to an increase in proinflammatory cytokines, tumor necrosis factor-alpha (TNF-α), interleukin-1 (IL-1), and interleukin-6 (IL-6) which stimulate central serotonin neurotransmission and are linked to hypothalamic-pituitary-adrenal overactivity increasing the risk of CVD and MI." (PMID 36237772, 2022). "Furthermore, serum corticosterone levels were markedly increased with IL-1β injection, while GR inhibitor RU486 reduced IL-1β-induced depression-like behavior and TNF-α and IL-6 expression." (PMID 36232376, 2022). "Individuals suffering from depression have elevated levels of pro-inflammatory cytokines, such as tumor necrosis factor alpha (TNF-α) and interleukin-6 (IL-6), but also other mediators, such as chemokines, and this seems to contribute to the onset of this disease." (PMID 35216147, 2022). "However, in general, it is known that pro-inflammatory cytokines are increased in major depressive disorder (MDD), with the most remarkable increases in IL-6, TNF, and C-reactive protein (CRP)." (PMID 35884835, 2022). "Using participants from the general population, the authors of a second study reported higher CSF levels of IL-6 and IL-8 in women with depression compared to those without depression." (PMID 36172507, 2022). "The investigation of 38 depression studies found that monocyte-derived, and other inflammatory cytokines (IL-1, IL-4, IL-6, and TNF) were significantly overexpressed in individuals with depression, while T cell derived cytokines (IL-10, and INF-γ) were uncorrelated with depression." (PMID 36206293, 2022). "Blocking IL-6 signaling in the periphery, but not in the brain, exerts rapid and long-lasting antidepressant-like effects in a mouse model of depression." (PMID 34979499, 2022). "Proinflammatory cytokines, such as IL-1β, IL-6, and TNF-α, might play crucial roles in the pathophysiology and treatment of depression." (PMID 35496318, 2022). "In relevant trials, high levels of interleukin (IL)-6 and tumor necrosis factor-alpha were found in HF patients with CD and depression, but not in HF patients free from these symptoms." (PMID 35887772, 2022). "CRP and IL-6 at the first point of follow-up predicted cognitive symptoms of depression at follow-up, while baseline symptoms of depression did not predict inflammatory markers." (PMID 35163141, 2022).
depression (continued). "In a prospective study, mentally healthy nine-year-olds with elevated IL-6 were more likely to be diagnosed with depression at the age of 18 years, compared to children without elevated IL-6." (PMID 36158450, 2022). "Similarly to manic episodes, serum levels of many inflammatory markers (CRP, TNF‐α, IL‐6, IL‐1β, sTNFR1, and CXCL10) are elevated during depressive episodes, and this alteration correlates with increased depression severity." (PMID 34590391, 2022). "A recent study investigated associations between levels of six cytokines (IL-1β, eotaxin, IL-15, IL-6, TNF-α, and leptin) and chronic multisite pain (CMP) in a sample of people living with HIV, but also incorporated PHQ-9 scores as a measure of depression in their regression models." (PMID 35618889, 2022). "These genes are involved in the complex pathological mechanism of depression, including the neurotransmitter system (e.g., HTR2A and SLC6A4), neurotrophin (e.g., BDNF), hypothalamic-pituitary-adrenal (HPA) axis (e.g., CRH), and inflammation (e.g., IL6, TNF)." (PMID 36072347, 2022). "In addition, proinflammatory cytokines such as IL-1, IL-6, TNF-α, and interferon (IFN)-γ enter the brain through multiple pathways to mediate depression-related psychiatric symptoms." (PMID 35813953, 2022). "This hypothesis is supported by studies reporting increased cerebrospinal fluid levels of the inflammatory markers interleukin (IL)-6, IL-8 and tumor necrosis factor alpha (TNF-α) in patients with ongoing depression." (PMID 36172507, 2022). "In pancreatic cancer patients, patients with depression exhibit higher serum IL‐6 levels than patients without depression." (PMID 34697903, 2022). "Taken together, the IL6/STAT3/Acp5 pathway modulated the excitability of PrL pyramidal neurons to change the adaption of PrL region, which critically involved in the development of comorbidity of neuropathic pain/depression." (PMID 35690777, 2022). "Specifically, microglia, the immune cells of the nervous system, are activated during neuroinflammation triggered by depression, resulting in the overexpression of various pro-inflammatory mediators, including tumor necrosis factor-α (TNF-α), interleukin-6 (IL-6) and NO, among others." (PMID 36330352, 2022). "Remarkably, an immunomodulatory effect of agomelatine on pro-inflammatory cytokines, including IL-6, has been demonstrated by our group in rats treated with lipopolysaccharide or exposed to chronic mild stress (CMS), a well-established model of depression." (PMID 36293308, 2022). "We also examined the mRNA level of inflammation-related factors, including IL-1β, IL-6, TNFα, and IL-10 in the PFC, dorsal hippocampus, and ventral hippocampus, which are three critical regions of the brain that are related to anxiety and depression." (PMID 35684068, 2022). "Proinflammatory cytokines (IL-1β, IL-6 and TNF-α) may be screening biomarkers in the prediction of treatment response in patients with depression." (PMID 36350802, 2022). "So far, there are many studies on the expression of serum IL-6 of depressive disorder, but its integration into routine clinical care has not yet been fully elucidated." (PMID 35615531, 2022). "The total HAMD score in patients with depressive disorder before treatment was positively correlated with serum IL-17, but not with IL-6." (PMID 35615531, 2022). "Also, numerous studies have shown that patients with major depression have elevated levels of TNF-α and that fluctuation of this pro-inflammatory cytokine (as well as that of IL-6) influences the mood behavior of the affected individuals (for review see." (PMID 34367160, 2021). "Notably, increased levels of pro-inflammatory cytokines such as IL-1β, IL-6 and TNF-α were markedly decreased in patients with depression receiving antidepressant treatment." (PMID 34889698, 2021).